HDGFL1 (HDGF like 1)
Synonyms: PWWP1; dJ309H15.1; Hdgfrp1; HRP-1
Tractability: No criterion of Open Targets' tractability assessment is met for any kind of drug.
Gene: Protein-coding gene on chromosome 6 (22,569,566 to 22,571,666, forward strand). Ensembl gene ENSG00000112273.
Subcellular location (Human Protein Atlas): Nucleoli fibrillar center; Nucleoplasm
Gene Ontology:
Biological process: chromatin remodeling
Genetic constraint (gnomAD): Missense variants: 422 observed, 325.9 expected, observed/expected ratio (o/e) 1.29, 90% interval 1.2 to 1.4. Synonymous variants: 190 observed, 143.64 expected, observed/expected ratio (o/e) 1.32, 90% interval 1.17 to 1.49.
Homologues: Orthologues: mouse Hdgfl1 (44% identical). Paralogues in human: HDGF (47% identical), HDGFL2 (35% identical), PSIP1 (32% identical), HDGFL3 (30% identical).
Diseases named in the same sentence as HDGFL1 in open-access papers:
HDGFL1 is named in the same sentence as 2 diseases in open-access papers, as found by Europe PMC text mining. Sharing a sentence is not in itself a finding about the gene and the disease. The quoted sentences say what the papers report.
atrial fibrillation (1 paper, 2021). A disorder characterized by an electrocardiographic finding of a supraventricular arrhythmia characterized by the replacement of consistent P waves by rapid oscillations or fibrillatory waves that vary in size, shape and timing and are accompanied by an irregular ventricular response. "Variants in HDGFL1 were recently shown to be significantly associated with atrial fibrillation (AF) and nominally (p<10–5) associated with MMVD in human populations." (PMID 34473707, 2021).
hepatoma (1 paper, 2015). "However, the gene near the SNP associated with extreme number of children is HDGFL1, a hepatoma-derived growth factor." (PMID 25742292, 2015). "The closest gene to this SNP is HDGFL1, a hepatoma-derived growth factor." (PMID 25742292, 2015).